ENSG00000291193 (novel transcript)
Synonyms: H2AFSP; HIST1H2APS1; bA317E16.5; H2AC2P
Gene: Long non-coding RNA gene on chromosome 6 (25,732,407 to 25,737,513, forward strand). Ensembl gene ENSG00000291193.
Gene Ontology:
Biological process: mRNA 3'-end processing by stem-loop binding and cleavage